ACE (angiotensin I converting enzyme)
Diseases named in the same sentence as ACE in open-access papers (continued):
Sharing a sentence is not in itself a finding about the gene and the disease.
diabetic nephropathy (continued). "B6 did not affect on the activities of ACE in diabetic nephropathy rats, but could upregulate ACE2 and ACE2 mRNA, which regulated the balance of circulation and local blood vessels, maintained renal blood flow and reached the purpose of anti-renal fibrosis finally." (PMID 29582239, 2018). "The activation of the classical RAS (via ACE activity) promotes inflammation and fibrosis, but the non-classical pathway (via ACE2 activity) protects against diabetic nephropathy." (PMID 39434906, 2024). "Patients with diabetic nephropathy had higher urinary levels of ACE2 than those without diabetic nephropathy, and use of ACE inhibitor and/or angiotensin receptor blockers did not affect urinary ACE2 levels." (PMID 22629438, 2012). "Early studies suggested a combination of ACE inhibitors and ARB may provide additional benefits in diabetic nephropathy, however, this combination is not clinically recommended due to complications of hyperkalemia and acute kidney injury." (PMID 38068400, 2023).
type 2 diabetes (227 papers, 2004 to 2026). "Elevated ACE expression was linked to maturity onset diabetes of the young, and HNF4A was enriched in pyruvate metabolism." (PMID 40995593, 2025). "An epidemiological study showed that patients treated with ACE inhibitors or angiotensin receptor blockers had a lower risk of developing type 2 diabetes compared to those using other antihypertensive medications." (PMID 40425574, 2025). "They demonstrated that in Asian and Chinese populations as well as type 2 diabetics, there is a correlation between the ACE I/D gene polymorphism and the risk of DN." (PMID 38844495, 2024). "For instance, ACE-DD genotypes demonstrate an elevated risk of developing inactivity-related type II diabetes, which is characterized by a substantially elevated blood concentration of glucose in the fasted state at rest." (PMID 36148310, 2022). "A significant relationship between D allele polymorphism in the ACE gene and advanced DR was reported in Japanese individuals with type 2 diabetes." (PMID 34177375, 2021). "The ACE/DD–ACE/ID polymorphism was able to predict the response to losartan in type 2 diabetic patients enrolled in the RENAAL trial, that is, patients with worse prognosis (D allele carriers) had the best response to losartan." (PMID 32823966, 2020). "Higher HOMA2-IR and known type 2 diabetes status at age 60–64 years were significantly associated with lower ACE-III scores." (PMID 31359084, 2019). "Our findings are of interest given the association of ACE-DD genotypes with a larger risk of developing type II diabetes." (PMID 26982073, 2016). "Although inhibitors of ACE activity are antihypertensive agents, they have been reported to reduce the risk of developing of type-2 diabetes." (PMID 26788368, 2015). "Over the past decades, many studies have been conducted to examine the association between ACE I/D polymorphism and nephropathy in type 1 and type 2 diabetes, but the results still remain inconsistent." (PMID 25587546, 2014). "Yang reported that interactions among RAS-related genes combination including ACE D/I polymorphism were associated with type 2 diabetes in a Chinese population." (PMID 24549414, 2014). "In patients with type 2 diabetes, ACE inhibitors and ARBs both diminish the risk for DN and reduce the occurrence of cardiovascular events." (PMID 28197454, 2014). "In spite of the several limitations of this study, the deletion allele of the ACE I/D polymorphism showed unfavorable renal prognosis in patients with proteinuric type 2 diabetes, which can be improved by losartan treatment." (PMID 25587546, 2014). "They included all of the studies that determined the genotype distribution of ACE I/D polymorphism in cases with type 1 or type 2 diabetes and nephropathy and in diseased controls or in healthy controls." (PMID 25587546, 2014). "Many studies showed that the genetic polymorphisms of some genes related to metabolism were associated with type 2 diabetes, and the ACE gene polymorphism was one of them." (PMID 24354906, 2013). "In recent years, the relationship between ACE gene polymorphism and type 2 diabetes was inconsistent among different reports." (PMID 24354906, 2013). "The relationship between ACE gene insertion/deletion polymorphism and diabetic retinopathy in Iranian patients with type 2 diabetes." (PMID 23401650, 2013). "On the other hand, large randomized clinical trials suggest that ACE inhibitors improve insulin resistance and reduce the incidence of new-onset type 2 diabetes in high-risk patients with cardiovascular disease." (PMID 23894285, 2013). "Methylene tetrahydrofolate reductase (MTHFR) is shown to act synergistically with angiotensin-I-converting enzyme (ACE) to modulate type 2 diabetes risk." (PMID 21960995, 2012).
type 2 diabetes (continued). "The result of this study supports the hypothesis that the DD genotype has a strong association with increased blood pressure and altered blood glucose level that implicates the ACE polymorphism plays an important role in the development of Type 2 diabetes." (PMID 37200278, 2023). "Homozygous carriers of the deletion allele in the gene for angiotensin-converting enzyme (ACE-DD) demonstrate an elevated risk to develop inactivity-related type II diabetes and show an overshoot of blood glucose concentration with enduring exercise compared to insertion allele carriers." (PMID 36148310, 2022). "The association between ACE I/D polymorphism and Type 2 diabetes has been rather controversial." (PMID 18637188, 2008). "Some studies have shown that angiotensin-converting enzyme (ACE) inhibitors or angiotensin receptor blockers are better first-line therapy for patients with MetS, especially when type-2 diabetes is present." (PMID 37614749, 2023). "The management of angiotensin-converting enzyme (ACE) inhibitors acts as an additional treatment benefit for patients having type II diabetes and microalbuminuria by reducing overall blood pressure." (PMID 36348831, 2022). "Angiotensin converting enzyme (ACE) inhibitors and angiotensin receptor blockers (ARBs) prevent microalbuminuria in normoalbuminuric type 2 diabetic patients." (PMID 34260595, 2021). "Renin–angiotensin system (RAS) blockade with angiotensin converting enzyme (ACE) inhibitors or angiotensin receptor blockers (ARBs) prevents the onset of microalbuminuria in patients with type 2 diabetes and normoalbuminuria." (PMID 34260595, 2021). "Over a follow-up period of 8 years, the proportion of subjects who developed type 2 diabetes were 2 (4.4%), 2 (4.3%) and 0 (0%) among ACE-inhibitors/CCBs/Thiazide-, ARBs/CCBs/Thiazide- and Perindopril/Amlodipine/Indapamide-treated patients, respectively." (PMID 34945217, 2021). "Some studies found that ACE inhibitor and ARB combination therapy reduced urinary albumin excretion (UAE) more effectively than ACE inhibitor or ARB monotherapy in type 2 diabetic patients with microalbuminuria or macroalbuminuria." (PMID 34260595, 2021). "We investigated the associations of metformin, statin, ACE inhibitor/angiotensin II receptor blocker (ARB), sulfonylurea (SU) derivatives and insulin use with the total plasma N-glycome in type 2 diabetes." (PMID 32616483, 2020). "Another study investigated the antihypertensive effects of eplerenone 50 or 100 mg/day added to ACE inhibitor therapy in patients with type 2 diabetes (n = 91 and n = 86, respectively) and reported significant reductions in BP from the baseline." (PMID 31239535, 2019). "Periconception exposure to potentially harmful medications, such as statins, ACE inhibitors or angiotensin receptor blockers, was less common in women with type 1 compared with type 2 diabetes (2.9% vs 8.6%; p < 0.001)." (PMID 28597075, 2017). "A silencer region (I-allele) within intron 16 of the gene for the regulator of vascular perfusion, angiotensin-converting enzyme (ACE), is implicated in phenotypic variation of aerobic fitness and the development of type II diabetes." (PMID 26982073, 2016). "Whereas in type 2 diabetes, there is more information available on the renoprotective effect of ARBs compared with ACE inhibitors." (PMID 28197454, 2014). "Conversely, marked decreases in PTX3 levels were associated with decreased albuminuria and improved flow-mediated dilatation following a 12 week intervention with ACE-inhibitors (ramipril) in type 2 diabetic patients." (PMID 23658833, 2013). "The ALiskiren Trial in Type 2 diabetes Using carDio-renal Endpoints (ALTITUDE) study evaluated the addition of aliskiren to an ACE inhibitor or an ARB in T2DM patients with CKD, CVD or both, but was stopped early due to safety concerns." (PMID 23866091, 2013).
type 2 diabetes (continued). "In The Netherlands for patients with type 2 diabetes prescription of an ACE inhibitor immediately after diagnosis should be considered if they do not have contraindications." (PMID 22022539, 2011). "The aim of our study was to assess the most cost-effective time to start an ACE inhibitor (or an angiotensin II receptor blocker [ARB] if coughing as a side effect occurs) in patients with newly diagnosed type 2 diabetes in The Netherlands." (PMID 22022539, 2011). "Data used to determine the cost-effectiveness of ACE inhibitors and ARBs in newly diagnosed type 2 diabetes." (PMID 22022539, 2011). "This modeling study shows that treating all patients with type 2 diabetes with ACE inhibitors (and more expensive ARBs in the event of cough) immediately after diagnosis is cost-effective and even reduces health care expenditures in the Dutch setting." (PMID 22022539, 2011). "By uncertain mechanisms, ACE inhibitors and angiotensin II receptor antagonists seem to decrease the incidence of type 2 diabetes." (PMID 20671994, 2010). "The primary goal of AdaPT is to compare the effects of two antihypertensive combination therapies, an ACE inhibitor based treatment with a diuretic- (or betablocker)-based treatment on the incidence of new-onset of type 2 diabetes." (PMID 18652658, 2008). "To test the hypothesis that high glucose induces inflammation in the gut and increases the risk of type 2 diabetes and SARS-CoV-2 viral entry, we first looked at the influence of glucose alone on the expression of ACE, ACE2, SGLT1, GLUT2 and TMPRSS2." (PMID 40227199, 2025). "The lack of a control group without ACE inhibitor and ARB was justified by results of previous randomized controlled trials demonstrating a protective effect of either ACE inhibitor or ARB treatment over placebo against microalbuminuria development in patients with type 2 diabetes." (PMID 34260595, 2021). "High ACE/ACE2 ratios in patients with type 2 diabetes and overt nephropathy were detected; thus, such changes might play a role in renal damage." (PMID 29157100, 2017). "The present study also found that the ACE gene I/D polymorphism was not a risk factor for type 2 diabetes in the elderly population, which was consistent with some reports." (PMID 24354906, 2013). "A recent meta-analysis concluded that the use of renin-angiotensin system antagonists (angiotensin-converting enzyme [ACE] inhibitors or angiotensin receptor blockers [ARBs]) may contribute to the prevention of type 2 diabetes." (PMID 17697384, 2007). "The combination of SGLT2is with renin–angiotensin system blockers, including ACE inhibitors and ARBs, has synergistic effects on the treatment of type 2 diabetes mellitus (T2DM)." (PMID 40630104, 2025). "In addition, the total soluble phenolic content, phenolic profile, antioxidant activity, and enzyme inhibitory activity against type 2 diabetes-relevant α-amylase and α-glucosidase and hypertensive-relevant angiotensin-I-converting enzyme (ACE), were also investigated." (PMID 39074098, 2024). "Genetically proxied ACE inhibition was associated with lower SBP (mm Hg per SD lower serum ACE concentration: −0.40, 95% CI −0.21 to −0.59, P = 4.2 × 10−5) and a lower risk of type 2 diabetes (odds ratio (OR) equivalent to 1 mm Hg lower SBP: 0.90, 95% CI 0.85 to 0.95, P = 1.3 × 10−4)." (PMID 35113855, 2022). "The observations identify reciprocal alterations of S473 and T308 phosphorylation of AKT as gatekeeper of a post-translational dysregulation of transcapillary glucose uptake in ACE-DD genotypes which may be targeted in personalized approaches to mitigate type II diabetes." (PMID 36148310, 2022). "In conclusion, the association between ACE gene I/D polymorphism and type 2 diabetes is not conclusive, as the inconsistent observations between ACE gene polymorphism and T2DM may be due to ethnic and geographical variations." (PMID 33507688, 2021).
type 2 diabetes (continued). "Furthermore, ACE inhibitors have been reported to reduce the risk of type-2 diabetes in nondiabetic patients at baseline; bradykinin enhances the responsiveness of both muscle fiber and adipocytes to insulin." (PMID 26788368, 2015). "In summary, clinical and experimental studies have shown that the inhibition of Ang II by ACE inhibitors or ARBs or antioxidants improve insulin sensitivity and glycemic control in diabetic patients and animals and reduce the incidence of new onset type 2 diabetes." (PMID 25928697, 2015). "Previous reports have linked the TEAD1, HECW1, SEMA6A, COL13A1 and LAMA2 genes with different age-related cancers, the PLAT and ACE genes with cardiovascular disease, the ACE and HECW1 genes with Alzheimer’s disease and the SEMA6A gene with type 2 diabetes." (PMID 36362280, 2022). "Inhibition of angiotensin-converting enzyme (ACE) activity was also reported in camu-camu fermented by L. plantarum, which suggests a beneficial effect of this product on treatment of type 2 diabetes." (PMID 34359473, 2021). "As for the strengths of this study, this is the first report investigating the association of total plasma N-glycome with metformin, statin, ACE inhibitors/ARB, SU derivatives and insulin use in type 2 diabetes." (PMID 32616483, 2020). "This study evaluated the antihypertensive effect, the albuminuria-lowering effect, and safety of esaxerenone in hypertensive patients with type 2 diabetes and albuminuria concomitantly receiving an ARB or ACE inhibitor." (PMID 31239535, 2019). "Additionally, the inhibition of the renin-angiotensin system with ACE inhibitors and angiotensin receptor blockers not only regressed LVH, but also delayed the onset of type 2 diabetes." (PMID 38167639, 2024). "The UK National Institute for Health and Care Excellence (NICE) recommends an ACE inhibitor as first-line antihypertensive in patients with type 2 diabetes with ARBs reserved for those in whom ACE inhibitors are not tolerated." (PMID 34533690, 2023). "Dual RAS blockade should not be preferred to ACE inhibitor or ARB monotherapy for the primary prevention of microalbuminuria in patients with type 2 diabetes and normoalbuminuria." (PMID 34260595, 2021). "The patients had type 2 diabetes with a history of non-Q-myocardial infarction receiving oral antidiabetic therapy and basic therapy, including an ACE inhibitor, a β-blocker, a statin, and an antiplatelet agent." (PMID 32341698, 2020). "PPARα or PPARγ agonists increase the levels of adiponectin, such as some treatments for cardiovascular diseases like angiotensin-converting enzyme (ACE) inhibitors, angiotensin II receptor antagonists, or rosiglitazone in type 2 diabetes and statins in hypercholesterolemic patients." (PMID 31354915, 2019). "They suggested that ACE I/D genotypes individually and in interaction with other RAS single nucleotide polymorphisms (angiotensinogen and angiotensin II type 1 receptor gene) modulate renoprotective efficacy of ACE inhibitor and ARB in type 2 diabetics depending on the status of proteinuria." (PMID 25587546, 2014). "One study carried out by taking biopsies of twenty type 2 diabetic patients and twenty healthy donors showed decreased ACE2 and increased ACE in tubulointerstitium and glomeruli in the diabetic patients with nephropathy indicating a pathologically important balance between the two enzymes." (PMID 22121476, 2012). "Second, transition rates from macroalbuminuria to ESRD with and without ACE inhibitors were not available for patients with type 2 diabetes." (PMID 22022539, 2011). "The goal of this study is to present a cost-effectiveness model, which determines the best time to start an ACE inhibitor in newly diagnosed patients with type 2 diabetes and without hypertension or heart failure in the Netherlands." (PMID 22022539, 2011).
type 2 diabetes (continued). "Moreover, the observed benefits were obtained in patients that received stable doses of angiotensin-converting enzyme inhibitor (ACE-i) or angiotensin II receptor blocker (ARB) therapy, which are other medications that can induce nephroprotective effects in type 2 diabetes." (PMID 34150796, 2021). "The BENEDICT study, carried out on patients with type 2 diabetes and hypertension, investigated the effectiveness of the ACE-inhibitor trandolapril as compared to the non-dihydropyridine calcium channel blocker verapamil given alone or in combination, over a mean 3.6 year follow-up period." (PMID 24092648, 2013).